PA2G4P4 (proliferation-associated 2G4 pseudogene 4)
Synonyms: PA2G4L1
Gene: Processed pseudogene on chromosome 3 (156,809,551 to 156,810,732, reverse strand). Ensembl gene ENSG00000230457.
Diseases named in the same sentence as PA2G4P4 in open-access papers:
PA2G4P4 is named in the same sentence as 4 diseases in open-access papers, as found by Europe PMC text mining. Sharing a sentence is not in itself a finding about the gene and the disease. The quoted sentences say what the papers report.
urothelial carcinoma (1 paper, 2020). A malignant neoplasm derived from the transitional epithelium of the urinary tract (urinary bladder, ureter, urethra, or renal pelvis). "In addition, a broad PA2G4P4 transcript distribution was found in all of the urothelial carcinomas analyzed for both LG and HG, while blood vessels in both types were negative." (PMID 32244410, 2020).
tumor (2 papers, 2017 to 2020). "Expression levels of PA2G4P4 were positively correlated with those of PA2G4 in all tumor types except KIRC, PRAD, and THCA – remarkable given that PA2G4 is on chromosome 12 and PA2G4P4 is on chromosome 3." (PMID 28673244, 2017). "The expression of PA2G4P4 was also correlated with that of NACA2 in about one third of the tumor types (data not shown)." (PMID 28673244, 2017). "The localization of PA2G4P4 RNA was almost overlapping with the immunostaining for EBP1 in both normal tissues and in the BlCa tumors, with the only exception of tumor blood vessels being immunoreactive for EBP1, but negative for the presence of PA2G4P4 transcripts." (PMID 32244410, 2020).
cancer (1 paper, 2017). A tumor composed of atypical neoplastic, often pleomorphic cells that invade other tissues. "Seven (PA2G4P4, ATP5EP2, FTH1P3, ANXA2P3, ANXA2P1, HNRNPA1P33, and HSP90B3P) of the 14 pseudogenes that our analysis revealed as important for pan-cancer classification were previously found to be differentially expressed in various cancers." (PMID 28673244, 2017).
PA2G4P4 also shares sentences with these, for which no sentence is quoted: bladder cancer (1 paper).